PRMT6 (protein arginine methyltransferase 6)
Diseases named in the same sentence as PRMT6 in open-access papers (continued):
Sharing a sentence is not in itself a finding about the gene and the disease.
gastric cancer (6 papers, 2021 to 2025). A primary or metastatic malignant neoplasm involving the stomach. "PRMT6 is linked to gastric cancer through its ability to increase global levels of H3R2me2a, a histone modification associated with altered chromatin structure and gene expression patterns that promote cancer progression." (PMID 40869229, 2025). "While these findings highlight PRMT6’s potential as a therapeutic target, its clinical relevance in gastric cancer remains to be fully elucidated." (PMID 40869229, 2025). "Conversely, upregulation of PRMT6 in gastric cancer cells has been found to enhance invasion by inhibiting the transcription of the oncogene protocadherin 7 (PCDH7) through increased levels of H3R2me2as." (PMID 39043634, 2024). "PRMT6 and H3R2me2a levels are elevated in gastric cancer (GC) and are correlated with poor prognosis." (PMID 34575100, 2021). "However, in gastric cancer PRMT6-KO-GC cells, knockdown of tumor suppressor gene PCDH7 promoted cell migration and invasion." (PMID 38167455, 2024).
hepatocellular carcinoma (6 papers, 2021 to 2025). A malignant tumor that arises from hepatocytes. "A recent study reported that silencing PRMT6 potentiated tumor metastasis, increased migration and invasion, and was resistant to cisplatin, 5-fluorouracil, and sorafenib treatment therapy in hepatocellular carcinoma (HCC)." (PMID 33670008, 2021). "PRMT6 is downregulated in Hepatocellular carcinoma (HCC) and this downregulation is correlated with aggressive features of HCC." (PMID 34575100, 2021). "PRMT6 also contributes to sorafenib in hepatocellular carcinoma (HCC)." (PMID 40465651, 2025). "In hepatocellular carcinoma (HCC), PRMT6 expression is negatively correlated with autophagic flux." (PMID 41154773, 2025).
viral infection (6 papers, 2020 to 2024). "Finally, we highlight how dysregulation of PRMT6 is implicated in various types of cancers and response to viral infections." (PMID 34575100, 2021). "In addition to these physiological functions, the dysregulation of PRMT6 is implicated in viral diseases, cancers and cardiac hypertrophy." (PMID 34575100, 2021). "A Viral infection not only upregulates PRMT6 protein levels, but also promotes the binding between PRMT6 and IRF3 and dampens the interaction between IRF3 and TBK1." (PMID 38257273, 2024). "To set up the conditions of viral infection, we performed a single intraperitoneal injection of amiR-Lsd1/Prmt6 at concentrations of 210 and 810 virion particles at 3 weeks of age." (PMID 36746939, 2023). "Several proteins of human immunodeficiency virus type I (HIV-1) are methylated by PRMT6, as part of the host response to suppress viral infection/propagation." (PMID 34575100, 2021). "Whether PRMT2 and PRMT6 cooperate with each other or function separately at different stages of viral infection to promote transcriptional silencing and viral latency remains to be elucidated." (PMID 37949879, 2023). "Aberrant expression of PRMT6 widely exists in cancers like lung, liver, gastric, and prostate cancer and viral infections." (PMID 33959602, 2021). "Viral infection and LPS also upregulated the protein levels of PRMT6." (PMID 33260152, 2020).
glioma (5 papers, 2018 to 2025). A benign or malignant brain and spinal cord tumor that arises from glial cells (astrocytes, oligodendrocytes, ependymal cells). "Taken together, these results suggest that the increase in PRMT6 might be associated with oncogenesis in glioma." (PMID 36792756, 2023). "In our selection of seven HRD-related genes, the high expression of PLK3, PRMT6, UNG, and FANCB is associated with poorer prognosis in glioma patients, whereas the high expression of POLR2F, INO80D, and PTEN is linked to better prognosis." (PMID 41417782, 2025). "Subsequently, we further analyzed the previous transcriptome sequencing data and found that silencing PRMT6 in glioma cells can reduce the expression of invasion-related molecules (TGFB1/2, MMP3/9/14, FN1, ROCK2, etc.)." (PMID 39043634, 2024). "The related mechanism shows that in glioma, PRMT6 is recruited by the transcriptional regulator CDK9 to the YTHDF2 promoter region and then synergistically promotes the transcriptional activation of YTHDF2 with CDK9." (PMID 38637831, 2024). "To investigate the potential correlation between PRMT6 expression in glioma tissues and their invasive characteristics, we analyzed PRMT6 expression levels in three glioma subtypes patients from the CGGA and TCGA databases." (PMID 39043634, 2024). "In this study, we found that PRMT6 promotes glioma migration, invasion, and EMT in vitro and in vivo." (PMID 38637831, 2024). "But little is known about the specific regulatory processes and potential molecular mechanisms of PRMT6 in gliomas." (PMID 38637831, 2024). "To understand the role of PRMT6 in glioma, we first explored its expression spectrum and prognostic significance in public databases such as TCGA, CGGA, and GTEXBrain." (PMID 38637831, 2024). "In our study, we confirm that PRMT6 promotes glioma cell migration, invasion, and EMT by transcriptionally activating YTHDF2." (PMID 38637831, 2024). "Taken together, these findings suggest that the expression of PRMT6 was highly positively correlated with invasion in glioma." (PMID 39043634, 2024). "Samples in the CGGA glioma database were categorized into “high PRMT6 expression” and “low PRMT6 expression” groups based on PRMT6 mRNA levels." (PMID 38637831, 2024). "Our study validates that PRMT6 transcriptionally activates YTHDF2, thereby promoting malignant phenotypes in glioma, a process that depends on PRMT6’s methyltransferase activity." (PMID 38637831, 2024). "Bioinformatics analysis and glioma sample detection results demonstrated that PRMT6 is highly expressed in mesenchymal subtype or invasive gliomas, and is significantly negatively correlated with their prognosis." (PMID 39043634, 2024). "Immunohistochemistry (IHC) results also demonstrate that PRMT6 expression increases with tumor grade in glioma." (PMID 38637831, 2024). "Immunohistochemistry (IHC) images also showed that PRMT6 was increased with increasing WHO grades in glioma, and higher than NBT." (PMID 36792756, 2023). "In our study, the PRMT6-CDC20-CDKN1B axis regulates glioma cell cycle progression is identified, therefore PRMT6 and CDC20 functionally play critical roles in GBM." (PMID 36792756, 2023). "To understand the expression profiles of PRMT6 in glioma tissues and their prognostic significance, we analyzed the sequencing data of glioma in CGGA, TCGA, and Gravendeel databases." (PMID 36792756, 2023). "Investigation of PRMT6 expression in glioma tissues demonstrated that PRMT6 is overexpressed, and elevated expression of PRMT6 is negatively correlated with poor prognosis in glioma/GBM patients." (PMID 36792756, 2023). "Here, we confirmed an elevated PRMT6 expression in higher WHO grades gliomas and in IDH-wild-type gliomas." (PMID 36792756, 2023). "In our study, we confirmed that PRMT6 acts as an oncogene in gliomas to facilitate GBM cell proliferation." (PMID 36792756, 2023).
glioma (continued). "Then, we investigated the prognostic significance of PRMT6 expression in patients with glioma, and the results showed that patients with high levels of PRMT6 had poorer overall survival compared to those with low PRMT6 expression." (PMID 36792756, 2023). "Our research results suggest that the PRMT6-YTHDF2-Wnt-β-Catenin axis may serve as a therapeutic target for glioma." (PMID 38637831, 2024). "These suggest PRMT6’s significant role in glioma development and progression." (PMID 38637831, 2024). "At present, there are still few studies on PRMT6 in gliomas." (PMID 38637831, 2024). "It suggests that the expression of PRMT6 in glioma may be related to cell proliferation and invasion." (PMID 39043634, 2024). "In addition, the elevated expression of PRMT1, PRMT2, PRMT4, and PRMT6 predicts poor prognosis in glioma patients." (PMID 30382083, 2018). "Interestingly, the expression levels of PRMT1, PRMT2, PRMT4, and PRMT6 in low-grade gliomas are significantly higher in IDH1/2 wild-type (WT) subgroups than the subgroups with the IDH1/2 mutations." (PMID 30382083, 2018). "IHC results indicate that the expression of PRMT6 may be related to the aggressiveness of glioma." (PMID 39043634, 2024). "The results suggest that both PRMT6 and YTHDF2 can activate the Wnt-β-Catenin pathway, implicating its involvement in the regulation of glioma migration, invasion, and EMT by PRMT6 and YTHDF2." (PMID 38637831, 2024). "While our study did not explore the overall impact of PRMT6 on m6A modifications in glioma cells, we found that PRMT6 affects the m6A modification of APC and GSK3β mRNA, as overexpression of PRMT6 reduces the m6A levels on these mRNAs." (PMID 38637831, 2024). "In this study, we reveal that the PRMT6-YTHDF2-Wnt-β-Catenin axis promotes migration, invasion, and EMT in gliomas, both in vivo and in vitro." (PMID 38637831, 2024). "In vitro functional experiments show that the PRMT6 small molecule inhibitor (EPZ020411) has an inhibitory effect on the migration, invasion, and EMT of glioma cells." (PMID 38637831, 2024). "To further clarify how PRMT6 transcriptionally activates YTHDF2 and then promotes malignant phenotypes in glioma, we conducted GSEA pathway analysis." (PMID 38637831, 2024). "PRMT6’s expression and prognostic significance in GBM were assessed using glioma public databases, immunohistochemistry (IHC), and immunoblotting." (PMID 38637831, 2024). "Moreover, we show that the impact of PRMT6 and YTHDF2 on glioma migration, invasion, and EMT depends on the activation of the Wnt-β-Catenin pathway." (PMID 38637831, 2024). "Furthermore, the results of immunoblotting on the freshly collected protein samples from gliomas revealed markedly higher PRMT6 protein levels compared to NBT, particularly in Grade III and IV gliomas." (PMID 36792756, 2023). "However, the specific mechanisms by which PRMT6 regulates glioma migration, invasion, and EMT are not yet reported." (PMID 38637831, 2024).
leukemia (4 papers, 2024 to 2026). A malignant (clonal) hematologic disorder, involving hematopoietic stem cells and characterized by the presence of primitive or atypical myeloid or lymphoid cells in the bone marrow and the blood. "In acute myelocytic leukemia (AML), IGF2BP2 maintains the function of human and murine leukemia stem cells (LSCs) via stabilizing PRMT6 mRNA in m6A-mediated manner(37." (PMID 41522349, 2026). "Moreover, IGF2BP3 stabilizes PRMT6 (protein arginine methyltransferase 6) mRNA, which in turn mediates histone H3R2me2a methylation and maintains the function of leukemia stem cells (LSCs)." (PMID 38902779, 2024). "In AML, IGF2BP2 stabilizes protein arginine methyltransferase 6 (PRMT6) and subsequently downregulates the expression of the lipid transporter major facilitator superfamily domain containing 2A (MFSD2A), thereby maintaining the function of leukemia stem cells." (PMID 38721006, 2024).
osteosarcoma (4 papers, 2012 to 2022). A usually aggressive malignant bone-forming mesenchymal neoplasm, predominantly affecting adolescents and young adults. "In PRMT6-deficient osteosarcoma cells U2OS cells, the expression of TSP-1 gene promoter was increased and the loss of H3R2me2a and the corresponding increase of H3K4me3 were observed at the TSP-1 promoter, inhibiting the migration of U2OS cells." (PMID 35311114, 2022). "PRMT6 also involves the methylation of arginine-2 of histone H3, so PRMT6 can regulate the cell cycle of osteosarcoma cells and promote tumor progression through arginine methylation of histone." (PMID 35311114, 2022). "Three independent siRNAs targeting PRMT6 were transfected into the human osteosarcoma cell line U2OS." (PMID 22916108, 2012). "To address a functional relation between PRMT6 and p21 we reduced PRMT6 expression by siRNA mediated knockdown in the human osteosarcoma cell line U2OS and analyzed protein expression level of all three members of the KIP/CIP family, namely p21, p27 and p57." (PMID 22916108, 2012). "Knockdown of PRMT6 expression in the human osteosarcoma cell line U2OS results in an accumulation of cells at the G2 checkpoint." (PMID 22916108, 2012). "It has been found that down-regulation of PRMT6 leads to up-regulation of p21 and p27, two members of the cyclin-dependent kinase (CDK) inhibitor CIP/KIP family, and accumulation of human osteosarcoma cell line U2OS at the G2 checkpoint." (PMID 35311114, 2022).
breast tumor (3 papers, 2023 to 2025). "These in vitro and in vivo results suggest that PRMT6 contributes to breast tumor growth by coordinating with key tumor regulatory genes in vitro and in vivo." (PMID 36941223, 2023). "Interestingly, a report showed that ALKBH5 is directly methylated at the R283 site by the ADMA modification of PRMT6, which thus promotes the formation of breast tumors." (PMID 39781264, 2025). "Furthermore, their work suggests that protein arginine methyltransferase 6 (PRMT6) directly methylates ABH5 at R283, thus leading to activation of this dioxygenase and subsequently promoting breast tumor growth." (PMID 39329974, 2024).
endometrial cancer (3 papers, 2021). Primary or metastatic malignant neoplasm involving the endometrium (mucous membrane that lines the endometrial cavity). "PRMT6 behaves as an oncogene to promote cell proliferation and migration in endometrial cancer via activation of the AKT/mTOR pathway." (PMID 34522186, 2021). "Depletion of PRMT6 inhibits the endometrial cancer cell proliferation and migration by negatively regulating AKT/mTOR signaling." (PMID 34575100, 2021). "PRMT6/miR-372-3p/Akt/mTOR signal pathway facilitated endometrial cancer process." (PMID 33869779, 2021).
HIV-1 infection (3 papers, 2013 to 2019). The type species of lentivirus and the etiologic agent of acquired immunodeficiency syndrome (AIDS). "This interaction between Tat and PRMT6 may impact upon pathogenic effects attributed to Tat during HIV-1 infection other than its function during transactivation." (PMID 23800116, 2013). "For example, Setdb2 and Prmt6 were involved in defense against Influenza A virus and HIV-1 infection." (PMID 31057555, 2019). "An in vitro study mimicking acute HIV-1 infection found PRMT6 to be downregulated immediately after infection, and its expression further decreased over time." (PMID 29449904, 2018).
melanoma (3 papers, 2020 to 2022). A malignant, usually aggressive tumor composed of atypical, neoplastic melanocytes. "PRMT6 was found to be expressed at reduced levels in melanoma compared to melanocytes, early studies have shown that the expression of methylthioadenosine phosphorylase (MTAP), which is involved in tumorigenesis, is significantly reduced in melanoma." (PMID 35311114, 2022).
Obesity (3 papers, 2020 to 2025). Accumulation of substantial excess body fat. "PRMT6 plays a role in the regulation of circadian rhythms, and its disruption is associated with metabolic dysfunctions such as obesity and insulin resistance." (PMID 40024983, 2025). "There are no previous reports on the role of PRMT1 and PRMT6 in obesity-induced skeletal muscle atrophy." (PMID 32316567, 2020).
ovarian carcinoma (3 papers, 2021 to 2023). A malignant neoplasm originating from the surface ovarian epithelium. "In another report, we found that the mRNA of PRMT6 in paclitaxel‐resistant ovarian cancer cells was lower than that in control ovarian cancer cells." (PMID 36999124, 2023). "PRMT6 is less abundant in paclitaxel resistant ovarian cancer cells compared to the sensitive cells." (PMID 34575100, 2021). "These low levels of PRMT6 lead to reduction of the repressive H3R2me2a modifications in the promoter region of G6PD resulting in the enhanced expression of G6PD which contributes to the paclitaxel resistance of the ovarian cancer cells." (PMID 34575100, 2021).
pancreatic cancer (3 papers, 2018 to 2025). "Similarly, the association of PRMT6 and p62 was augmented in pancreatic cancer cells after ferroptosis induction." (PMID 38994016, 2024). "As a result, suppression of PRMT6 or p62 remarkably sensitized ferroptosis in pancreatic cancer both in vitro and in vivo." (PMID 38994016, 2024). "Due to the positive correlation and high expression of p62 and PRMT6 compared to other cancer cell lines, pancreatic cancer was further selected to verify the role of PRMT6-mediated p62 ADMA in ferroptosis." (PMID 38994016, 2024). "Knockdown of p62 or PRMT6 notably sensitized pancreatic cancer cells to ferroptosis both in vitro and in vivo through suppressing Nrf2 signaling." (PMID 38994016, 2024). "In the current study, we attempt to further our understanding of the molecular mechanisms by which PRMT3 and PRMT6 modulate the GEM resistance in pancreatic cancer." (PMID 30577570, 2018). "Furthermore, as a member of the type I PRMT family, PRMT6 also plays a significant role in various cancers, including breast cancer, lung cancer, hepatocellular carcinoma, and pancreatic cancer." (PMID 39964832, 2025). "Finally, both PRMT6 and p62 are highly expressed in pancreatic cancer cells, resulting in the elevated PRMT6-mediated p62 AMDA, which greatly attenuates the efficiency of ferroptosis induction." (PMID 38994016, 2024). "Therefore, targeting PRMT6-mediated p62 ADMA should be considered in cancer treatments resulting in ferroptosis activation in pancreatic cancer, and probably other cancers." (PMID 38994016, 2024). "Therefore, inhibition of PRMT6-mediated p62 ADMA could significantly sensitize pancreatic cancer cells to ferroptosis both in vitro and in vivo." (PMID 38994016, 2024). "Therefore, targeting PRMT6-mediated p62 ADMA might be a potential synergistic strategy for ferroptosis-inducing therapies in pancreatic cancer, and probably other cancers." (PMID 38994016, 2024). "As a result, suppression of p62 or PRMT6 increased cytotoxicity and augmented lipid ROS after ferroptosis induction, indicating that inhibition of PRMT6-mediated p62 ADMA sensitized ferroptosis in pancreatic cancer cells." (PMID 38994016, 2024). "In addition to EHMT2, we found that two other members of the PRMT family, PRMT3 and PRMT6, are highly upregulated in GEM-resistant pancreatic cancer cells." (PMID 30577570, 2018).
bladder cancer (2 papers, 2021 to 2022). "When PRMT1 and PRMT6 genes were knocked down, the growth of bladder cancer cell lines (SW780 and RT4) was significantly inhibited, and the cells in the S phase were significantly reduced, while those in G0 and G1 phases were increased simultaneously." (PMID 35311114, 2022). "PRMT6 levels are elevated in several types of cancers and the depletion of PRMT6 inhibits the proliferation of lung and bladder cancer cells." (PMID 34575100, 2021). "Meanwhile, real-time quantitative RT-PCR analysis of gene microarray data suggested that PRMT1 and PRMT6 could lead to the carcinogenesis of bladder cancer by regulating RNA processing and DNA replication." (PMID 35311114, 2022). "Therefore, PRMT1 and PRMT6 may be a promising target for bladder cancer therapy, and their inhibitors may be ideal candidates for molecular targeted therapy of bladder cancer." (PMID 35311114, 2022).
brain tumors (2 papers, 2023 to 2024). "Compared with control tumors, we observed fewer microtumor protrusions, clearer tumor borders, and a slower invasive growth trend in PRMT6-silenced brain tumors." (PMID 39043634, 2024). "In previous reports, there are relatively rare studies on PRMT6 in brain tumors." (PMID 36792756, 2023).